KIT (KIT proto-oncogene, receptor tyrosine kinase)
Diseases named in the same sentence as KIT in open-access papers (continued):
Sharing a sentence is not in itself a finding about the gene and the disease.
tumor (continued). "Here, we studied the tumor cell-intrinsic role of KIT in three-dimensional patient-derived tumor organoids (PDOs) by generating PDO variants in which the KIT gene was either deleted (by CRISPR-Cas9-mediated gene editing), or overexpressed (by using a lentiviral expression construct)." (PMID 35842424, 2022). "Likewise, in case 6, a c-KIT p.Y578_D579dup Exon 11 insertion mutation was detected by PCR in the primary tumor." (PMID 35885469, 2022). "Subsequent tumor sequencing, using a panel-based test upon disease progression, demonstrated her known KIT exon 11 mutation (unknown)." (PMID 34504655, 2021). "Our aims were to comprehensively analyze genomic changes in Chinese GISTs and to identify rare novel gene mutations in KIT/PDGFRA or other tumor-related genes that may take part in the development and chemoresistance of GIST from an omics viewpoint." (PMID 34805171, 2021). "In addition, patients with KIT mutated GISTs tended to have an increased tumor size and a higher mitotic index and risk grade as compared with those with PDGFRA and WT-mutated GISTs." (PMID 34956906, 2021). "Thus, our results demonstrate that a significant fraction of GIST patients actually affected by a KIT–mutant tumor are missed by the state-of-the-art molecular diagnostic protocols due to the limits of the standard techniques in use." (PMID 32391261, 2020). "Finally, targeted therapy with imatinib was induced in presence of a druggable c-KIT mutation, leading to a considerable response of all tumor sites that is still ongoing." (PMID 32457834, 2020). "Remarkably, a slight increase in the AF of the primary KIT exon 11 mutation (1%) and the secondary KIT exon 17 Y823D (0,45%) was observed by ddPCR on the third timepoint (10.2016) before radiological tumor progression, thereby anticipating in 2 months the eventual disease progression." (PMID 32024476, 2020). "Interestingly, both patients that displayed partial response had a KIT exon 11 mutations in their primary tumor, in contrast to the other patients." (PMID 32535637, 2020). "Thus, patient 11 disease progression after 2 months of regorafenib evidenced in plasma the emergence of the multi-resistant KIT exon 11 D816V mutation that was present in tumor tissue prior to the initiation of the therapy." (PMID 32024476, 2020). "However, in clinical practice, some GISTs carry the KIT exon 11 mutation but still show tumor metastasis and rapid growth after surgical resection and imatinib therapy." (PMID 32697050, 2020). "The KIT exon 11 mutation detected in plasma matched with its respective mutation in tumor tissue." (PMID 32024476, 2020). "In addition, it has been reported that loss of PI3 kinase association blocks GISTs tumor development in knockin mice carrying germline KIT mutant." (PMID 32082541, 2020). "Although the detected KIT mutations are different from activating mutations found in other KIT-dependent neoplasms, our data suggest that KIT-inhibitors might have a role in treating BRAF-wt LCH patients." (PMID 32372223, 2020). "In addition, patients with germline KIT mutations sometimes present with skin hyperpigmentation, dysphagia, or gastrointestinal autonomic nerve tumors, such as paragangliomas." (PMID 31100836, 2019). "We hypothesize that based on the allele frequency of SDHA and KIT mutations the tumor is best regarded as SDH‐deficient GIST in which the SDHA mutation represents the most likely driver mutation." (PMID 31124195, 2019). "There were 6 tumors with coexisting mutations of the same gene (1 with 2 BRAF, 2 with 2 NRAS, 1 with 2 PIK3CA, 1 with 2 KIT, and 1 with 3 KIT mutations), and 26 tumors with coexisting mutations of different genes, including a tumor with 2 NRAS and one PIK3CA mutation." (PMID 31277584, 2019).
tumor (continued). "Notably, 1 patient with KIT exon 9 mutant GIST tumor (Y503_F504insAY mutation) had a 27% reduction in tumor burden after cycle 1, but withdrew from the trial by choice due to persistent GI symptoms before the follow-up evaluation." (PMID 30081867, 2018). "Although KIT and PDGFRA mutations are likely of key importance in the molecular pathogenesis of GISTs, identical single KIT or PDGFRA mutations may be associated with widely different tumour mitotic counts and GIST patient survival outcome." (PMID 29377440, 2018). "KIT was the only mutation noted upon tumor progression during regorafenib." (PMID 28915719, 2017). "Using a representative paraffin block of the tumor, we performed mutation analyses for exons 9, 11, 13, and 17 of the c-KIT gene by polymerase chain reaction (GeneAmp PCR System 2700, USA) using a direct sequencing method (Applied Biosystems 3500 Genetic Analyzer, USA)." (PMID 28351362, 2017). "Mutations in BRAF were identified in 8.4% and KIT in 7.0% of tumor samples." (PMID 28380455, 2017). "However, the first biopsy or surgical tumor tissues analyzed at the initial diagnosis harbored only primary KIT mutations." (PMID 29100343, 2017). "Moreover, among A1 patients with a tumor size >5 cm, those carrying a KIT or PDGFRA mutation (n = 11) had a worse prognosis than the WT (n = 3), the 2-year RFS rates being 58 and 100 % respectively." (PMID 26867653, 2016). "HIF-1α and VEGF association with Axl, ALDH1, and c-KIT markers of tumor angiogenesis." (PMID 26760782, 2016). "Four of the 19 cases had intratumoral KIT mutational heterogeneity with concurrent wild-type and mutant tumor cells, which may have triggered polyclonal evolution and metastasis and unique therapeutic sensitivity." (PMID 26848617, 2016). "However, a recent study showed that tumor-specific mutations in KIT or PDGFRA can be detected and quantified in circulating cfDNA in plasma samples from patients with GIST." (PMID 27443349, 2016). "The primary analysis revealed that individuals with a primary KIT exon 9 mutation in their tumor achieved better clinical outcomes during treatment with sunitinib than those with a primary KIT exon 11 mutation, across all three efficacy measures (PFS, OS, and ORR)." (PMID 26772734, 2016). "The genetic and epigenetic analysis of a low-risk GIST presented here suggests that a typical activating KIT mutation together with loss of one of chromosomes 14 might indeed be sufficient to trigger formation of clinically symptomatic tumours." (PMID 26102504, 2015). "We hypothesized that there may be other genomic alterations besides the KIT mutation and loss of chromosome 14q that drove the formation of the studied tumour." (PMID 26102504, 2015). "However, the clinical behaviour of GIST with identical KIT mutations can widely vary from clinically silent small tumours incidentally discovered at autopsy in elderly patients to locally invasive tumours, some of which metastasise, in particular to the liver." (PMID 26102504, 2015). "KIT mutations were reported to associate with tumor metastasis and poor clinical outcome in GISTs." (PMID 24674052, 2014). "However, an increased risk for larger tumor size (>5 cm) and higher mitotic activity (>5) was observed in the KIT mutation-positive subgroup (1.74 (95% CI, 1.20 to 2.53; P = 0.003) and 2.00 (95% CI, 1.08 to 3.68; P = 0.03), respectively)." (PMID 24674052, 2014). "Tumor metabolic change on 18F-FDG-PET/CT was also associated with KIT mutational status." (PMID 25609545, 2014). "However, loss of KIT expression has been observed with progression of disease from superficial and invasive to metastatic stages, suggesting that KIT possesses tumor suppressive functions." (PMID 24416617, 2013). "In patients with available data on tumor genotype, we found consistently with results already reported that the mutational status had significant impact on prognosis, with the best results for KIT exon 11 mutants in terms of PFS and OS." (PMID 24217870, 2013).
tumor (continued). "This acquired resistance may be attributable to the development of secondary KIT mutations in residual tumor tissue." (PMID 23637977, 2013). "Therefore, we examined associations between 522 single nucleotide polymorphisms and seven KIT or PDGFRA tumor mutations types." (PMID 24159917, 2013). "Amplification of the KIT genomic region was observed in all four samples, while homozygous loss (log2ratio <−3.0) of 2q24.1 and Xp22.31 was observed in the 3.8N tumor populations present in the BLC and Lung LLL suggesting that these clones were further evolved from the BRFL clone." (PMID 23029135, 2012). "Interestingly, case M29, despite loss of KIT allele in the tumor tissue showed strong immunostaining and 1.61 fold higher levels of its transcript." (PMID 22672386, 2012). "Notably, M29 tumor tissue showed copy number value of 1.2 and 95% of the cells showing KIT/nucleus fluorescence signal ratio of ≤ 1.4, suggesting loss of KIT allele, akin to hemizygosity s." (PMID 22672386, 2012). "In the group of 89 patients, whose initial tumor mutational status was evaluated, 58.4% of GISTs had an exon 11 KIT mutation, 16.9% had an exon 9 KIT mutation, 13.5% had PDGFRA gene mutation (11 of 12 cases had D842V mutation) and in 11.2% of tumors we have not detected any mutations (wild-type)." (PMID 22439647, 2012). "Estimated 1-year PFS and 2-year OS according to primary tumor genotype were as follows: KIT exon 9 mutations - 68%/73% (median 65.5/151.5 weeks), wild type - 57%/70% (median 50.5/121 weeks), KIT exon 11 mutations - 34%/34% (median 36.8/65.5 weeks) and PDGFRA mutations - 15%/25% (median 9/40 weeks)." (PMID 22439647, 2012). "In addition, mutation analysis showed that the tumor had KIT exon 11 deletions, a genotype shown to be associated with adverse outcomes after surgery." (PMID 21975443, 2011). "In addition, patients whose tumor expressed a secondary mutation affecting exons 13 or 14 had a better outcome than those whose tumor had a KIT exon 17 or 18 mutation." (PMID 21605429, 2011). "Tumour characteristics, including the presence of the KIT exon 10 M541L variant, may have influenced tumour control in this small series but this needs to be confirmed and better explained." (PMID 20664593, 2010). "The distribution of PDGFRA mutant tumours between the low- and high-risk categories was significantly different from that of KIT mutant or wild-type tumours when using the AFIP classification (P=0.005, Kruskal–Wallis test), but not when using the NIH classification (P=0.452, Kruskal–Wallis test)." (PMID 20588273, 2010). "Tumour characteristics, including the presence of a KIT exon 10 M541L variant, may influence tumour control but this needs to be confirmed and better explained." (PMID 20664593, 2010). "Six mucosal tumours (38%) harboured a KIT mutation, and these spanned across all exons tested." (PMID 20372153, 2010). "Two recent autopsy series have shown that the incidence of GIST may be as high as 50% in stomach specimens; in one of these series, canonical KIT or PDGFRA mutations were found in 50% of assessable tumours." (PMID 20588273, 2010). "Of these, 13 and 8 tumours had KIT or PDGFRA mutations, respectively." (PMID 19943934, 2009). "However, to further investigate this potential association, we evaluated c-KIT copy number among patients with available archival tumour material who were treated on a previously published phase 2 study." (PMID 19904263, 2009). "Higher free AUC also predicted a higher probability of therapeutic response in GIST (odds ratio 2.6±1.1; P=0.026) when taking into account tumour KIT genotype (strongest association in patients harbouring exon 9 mutation or wild-type KIT, known to decrease tumour sensitivity towards imatinib)." (PMID 18475296, 2008). "Patients harbouring tumours characterised by an exon 11 KIT mutation may benefit from a better response to imatinib compared to other subgroups, notably exon 9 mutants or wt KIT tumours." (PMID 18475296, 2008).
tumor (continued). "The survival of patients with metastatic and inoperable malignant gastrointestinal stromal tumours (GIST), particularly those whose tumours have KIT exon 11 mutations, has improved dramatically since the introduction of imatinib mesylate into treatment protocols." (PMID 17533389, 2007). "The molecular genetic part of our study included search for the presence of Y-chromosome material by fluorescence in situ hybridisation (FISH), and mutational analysis of the KIT oncogene (exon 17, codon 816), which is often mutated in testicular GCTs, in a subset of tumour DNA samples." (PMID 17274819, 2007). "The locations of these c-KIT mutations vary between the different neoplastic diseases." (PMID 16579858, 2006). "In conclusion, although KIT gain-of-function mutations play a major role in GIST oncogenesis, we show that KIT activation in these tumours is unrelated to the presence of these mutations, and may result from an autocrine/paracrine mechanism." (PMID 16570044, 2006). "It demonstrated an ORR of 22%–30% in the overall population and 24%–37% in patients with KIT exon 11 mutations, when used as a second-line treatment for patients who progressed or were intolerant to Imatinib therapy, providing an opportunity for tumor reduction in these patients." (PMID 40303927, 2025). "One PDX model could be established from a tumor sample with a secondary KIT exon 16 mutation and a primary KIT exon 9 mutation (UZLX-GIST73), and an imatinib-resistant PDX model could be established with a primary KIT exon 11 mutation, and secondary KIT exon 11 and exon 17 mutations (UZLX-GIST9)." (PMID 39853155, 2025). "Although the anti‐tumour effects of toceranib are comparable to those of vinblastine in canine MCTs with or without KIT mutations, the relationship between the therapeutic response to toceranib and KIT mutation status in feline MCT remains unclear." (PMID 39177283, 2024). "However, imatinib becomes ineffective once tumor accumulates secondary mutations of KIT." (PMID 38313431, 2023). "However, gain-of-function mutations in the KIT gene can promote tumour formation and progression." (PMID 35610596, 2022). "Furthermore, whether individual mutations that have been previously reported are truly linked to c-KIT activation or tumor cell proliferation is unclear." (PMID 36138037, 2022). "Acquisition of this mutation early during haematopoiesis may cause multilineage involvement of haematopoiesis by KIT D816V, which has been associated with higher tumour burden and additional mutations in other genes, leading to an increased rate of transformation to advanced SM." (PMID 35626091, 2022). "This included collating studies of Sanger sequencing hot spot regions in BRAF, NRAS, and KIT, identifying rare but recurrent functionally relevant non‐hot spot variants, which otherwise would not have been uncovered, highlighting the importance of analyzing larger tumor collections." (PMID 35229492, 2022). "Interestingly, the dural part of the tumor (middle) revealed a KIT p.D816H mutation." (PMID 34072863, 2021). "Interestingly, KIT mutations were associated with histological subtype and tumor site." (PMID 34102999, 2021). "In our study, including KIT exon 11, 13, and 17 mutation GISTs, which were truly well responsive to imatinib therapy at a dosage of 400 mg daily, KIT exon 9 mutation GISTs were also well responsive to imatinib therapy at a dosage of 600 mg daily, with obvious shrinkage of their tumor size." (PMID 32264886, 2020).
tumor (continued). "Moreover, in line with IHC data, an analysis focused on KIT-mutated genotypes highlighted the influence of tumor location on susceptibility to immune infiltration: intestinal KIT-mutated tumors featured higher infiltration scores compared with the gastric KIT-mutated counterpart." (PMID 33048845, 2020). "Furthermore, KIT activation may be associated with tumour aggressiveness via the activation of Wnt/β-catenin signalling." (PMID 31370857, 2019). "Consequently, c-KIT mutations in tumor tissues are related to shorter survival times." (PMID 29915788, 2018). "Once mutated, KIT may encode tyrosine kinase receptors in which the tyrosine kinase domain can be activated in the absence of stem cell factor signaling, thereby stimulating excess, unregulated proliferation of the host tumor cells." (PMID 23637977, 2013). "This limitation may, however, be minor, because acquired KIT mutations are common in imatinib-resistant GIST reducing the applicability of the primary tumour mutation analysis, and because recent studies show that multiple acquired mutations are often present in imatinib-resistant GIST." (PMID 21540861, 2011). "Moreover, tumor shrinkage could be observed even in cases with less favorable KIT/PDGFRα mutational status, with an overall median tumor reduction of 34%." (PMID 19646278, 2009). "Secondary mutations in KIT and PDGFRA, compensatory activation of parallel signaling pathways, and tumor microenvironment-mediated resistance continue to limit long-term efficacy of current TKIs." (PMID 41517566, 2026). "Tumor presence was associated with increased expression of LH and FSH receptors and c-KIT, while angiogenic and proliferative factors (PCNA, Ki-67, IGF-1, VEGF, and ERα) showed lower expression." (PMID 42121783, 2026). "The proportion of successfully tested tumours that were NRAS and KIT mutated were 30.8% (1811/5887) and 5.8% (148/2560)." (PMID 41378737, 2026). "Contrary to expectations, imatinib showed minimal tumor suppression (about 1% inhibition rate, p = 0.8844), while KIT-d-MMAE significantly inhibited tumor growth (about 70% inhibition rate, p < 0.0001), outperforming both imatinib and VcMMAE." (PMID 40963922, 2025). "CD117 expression in AS is thought to represent oncofetal expression, where tumor cells revert to a phenotype resembling fetal endothelial cells that exhibit KIT positivity." (PMID 40666093, 2025). "In a reanalysis of a single-cell dataset of GIST 36, it was observed that KIT expression is predominantly found in the tumor cells." (PMID 40963922, 2025). "Sarcoma European Latin‐American Network (SELNET) guidelines for GIST recommend KIT and PDGFRA tumor mutational analysis for candidates for systemic therapy but does not provide specific guidelines on SDH IHC testing." (PMID 39927693, 2025). "Plasma concentration of M4205 as well as levels of autophosphorylated KIT in tumor tissue was determined at different time points after the last treatment at study end." (PMID 40018846, 2025). "A dose-dependent reduction of phosphorylated KIT in tumor tissue was observed over time which translated also into dose-dependent inhibition of downstream ERK1/2 phosphorylation, in line with the cellular data." (PMID 40018846, 2025). "GISTs are typically caused by mutations in KIT or PDGFR genes, leading to inappropriate tyrosine kinase activation and promoting tumor development." (PMID 40951360, 2025). "In summary, imatinib resistance in GISTs arises from both intrinsic and acquired mechanisms, most notably through secondary mutations in KIT or PDGFRA and tumor heterogeneity." (PMID 40733131, 2025). "It works by slowing down or stopping the growth of tumor cells through the inhibiting tyrosine kinases, including KIT and PDGFRα." (PMID 40696704, 2025). "In 2024, disease progression was observed with residual KIT mutation (VAF 1.10%) and new-onset ETV6:NTRK3 fusion (VAF 35.29%) detected by circulating tumor DNA (ctDNA) analysis." (PMID 40900786, 2025).